SF3B6 (splicing factor 3b subunit 6)
Description:
Component of the 17S U2 SnRNP complex of the spliceosome, a large ribonucleoprotein complex that removes introns from transcribed pre-mRNAs. The 17S U2 SnRNP complex (1) directly participates in early spliceosome assembly and (2) mediates recognition of the intron branch site during pre-mRNA splicing by promoting the selection of the pre-mRNA branch-site adenosine, the nucleophile for the first step of splicing. Within the 17S U2 SnRNP complex, SF3B6 is part of the SF3B subcomplex, which is required for 'A' complex assembly formed by the stable binding of U2 snRNP to the branchpoint sequence in pre-mRNA. Sequence independent binding of SF3A and SF3B subcomplexes upstream of the branch site is essential, it may anchor U2 snRNP to the pre-mRNA. Within the 17S U2 SnRNP complex, SF3B6 directly contacts the pre-mRNA branch site adenosine for the first catalytic step of splicing. SF3B6 stabilizes the intron branch site-U2 snRNA duplex, thereby promoting-binding of introns with poor sequence complementarity. Also acts as a component of the minor spliceosome, which is involved in the splicing of U12-type introns in pre-mRNAs.
Synonyms: SF3B14a; SAP14; SF3B14; CGI-110; HSPC175; HT006; P14; SAP14a
Tractability: Small molecule: a structure with a bound ligand is known; it has a binding pocket of medium quality. PROTAC: UniProt records ubiquitination sites on it; ubiquitination databases record sites on it; its protein half-life has been measured.
Target class: Other nuclear protein
Gene: Protein-coding gene on chromosome 2 (24,067,579 to 24,076,464, reverse strand). Ensembl gene ENSG00000115128.
Subcellular location: Nucleus
Subcellular location (Human Protein Atlas): Nucleoplasm
Pathways (Reactome):
Metabolism of RNA: mRNA Polyadenylation; mRNA Splicing - Major Pathway; mRNA Splicing - Minor Pathway
Chromatin organization: CHD1 and CHD2 subfamily
Disease: Dengue Virus-Host Interactions
Gene Ontology:
Molecular function: mRNA binding; protein binding; RNA binding; nucleic acid binding
Biological process: mRNA splicing, via spliceosome; spliceosomal snRNP assembly; spliceosome conformational change to release U4 (or U4atac) and U1 (or U11); U2-type prespliceosome assembly
Cellular component: nucleoplasm; nucleus; precatalytic spliceosome; spliceosomal complex; U11/U12 snRNP; U12-type catalytic step 2 spliceosome; U12-type precatalytic spliceosome; U12-type spliceosomal complex; U2-type catalytic step 1 spliceosome; U2-type spliceosomal complex; U2 snRNP
Genetic constraint (gnomAD): Loss-of-function variants: 2 observed, 11.13 expected, observed/expected ratio (o/e) 0.18, 90% interval 0.072 to 0.57. The upper end of that interval is the gene's LOEUF score, 0.57, which puts it in group 2 of 6, group 1 being the genes least tolerant of losing a copy. Missense variants: 41 observed, 106.86 expected, observed/expected ratio (o/e) 0.38, 90% interval 0.3 to 0.5. Synonymous variants: 33 observed, 38.28 expected, observed/expected ratio (o/e) 0.86, 90% interval 0.65 to 1.15.
Homologues: Orthologues: chimpanzee SF3B6 (100% identical), dog SF3B6 (100% identical), guinea pig SF3B6 (100% identical), macaque SF3B6 (100% identical), mouse Sf3b6 (100% identical), pig SF3B6 (100% identical), rabbit SF3B6 (100% identical), zebrafish sf3b6 (100% identical), tropical clawed frog sf3b6 (99% identical), rat Sf3b6 (95% identical), Drosophila melanogaster Sf3b6 (71% identical), Caenorhabditis elegans sftb-6 (68% identical).
Diseases named in the same sentence as SF3B6 in open-access papers:
SF3B6 is named in the same sentence as 15 diseases in open-access papers, as found by Europe PMC text mining. Sharing a sentence is not in itself a finding about the gene and the disease. The quoted sentences say what the papers report.
ovarian carcinoma (2 papers, 2025). A malignant neoplasm originating from the surface ovarian epithelium. "Conversely, low SF3B6 expression was linked to shorter OS in ovarian cancer (OV) (P < 0.05)." (PMID 40356980, 2025). "Similarly, regulators of RNA processing and splicing such as TCEA1, SF3B6, ZCRB1, PNO1, and DCAF13 were overexpressed, indicating dysregulation of mRNA metabolism and splicing fidelity in ovarian cancer." (PMID 41228302, 2025). "Additionally, we retrieved protein expression data for SF3B6 from the UALCAN database, which indicated a significant increase in SF3B6 protein levels in liver cancer, glioblastoma, head and neck cancer, lung cancer, ovarian cancer, colon cancer, and breast cancer compared to normal tissues." (PMID 40356980, 2025).
breast carcinoma (1 paper, 2025). "Our findings align with earlier research, demonstrating that SF3B6 was significantly elevated in the majority of tumor tissues, including those from breast cancer, pancreatic cancer, lung cancer, liver cancer, and so on." (PMID 40356980, 2025). "In breast cancer, upregulation of SF3B6 expression is related to worse prognosis." (PMID 40356980, 2025). "Previous studies of SF3B6 in tumors have been limited to PDAC, breast cancer, and NSCLC." (PMID 40356980, 2025).
hepatocellular carcinoma (1 paper, 2025). A malignant tumor that arises from hepatocytes. "Currently, there is no systematic multi-omics study exploring the diagnostic, prognostic, and immunotherapy predictive value of SF3B6 in pan-cancer, nor is its role in hepatocellular carcinoma (HCC) clear." (PMID 40356980, 2025).
liver cancer (1 paper, 2025). An epithelial or non-epithelial malignant neoplasm that arises from the liver. "Similarly, the Western blotting results displayed that the protein expression levels of SF3B6 were elevated in these liver cancer cell lines." (PMID 40356980, 2025). "Moreover, SF3B6 was highly expressed in liver cancer cells, promoting the proliferation, migration, and invasion of cancer cells, inhibiting apoptosis, and regulating the transition from the S phase to the G2M phase of the cell cycle." (PMID 40356980, 2025). "To investigate the expression of SF3B6 in liver cancer cell lines, we conducted RT-qPCR and Western blotting on a normal human liver epithelial cell line (THLE-3) and three liver cancer cell lines: Sk-hep1, Huh7, and HCCLM3." (PMID 40356980, 2025).
non-small cell lung carcinoma (1 paper, 2022). A group of at least three distinct histological types of lung cancer, including non-small cell squamous cell carcinoma, adenocarcinoma, and large cell carcinoma.
cancer (3 papers, 2017 to 2025). A tumor composed of atypical neoplastic, often pleomorphic cells that invade other tissues. "To investigate the clinical relevance of SF3B6, we conducted a receiver operator characteristic (ROC) analysis to assess its diagnostic potential across various cancer types." (PMID 40356980, 2025). "We then employed Gene Set Variation Analysis (GSVA) to examine the correlation of SF3B6 with HALLMARK pathways across different cancers." (PMID 40356980, 2025). "The analysis indicated that elevated SF3B6 expression was associated with shorter OS in several cancers, including ACC, HNSC, KIRP, LIHC, LUAD, and PAAD." (PMID 40356980, 2025). "The results were consistent with those obtained from the ESTIMATE algorithm, indicating that SF3B6 gene expression was negatively linked to tumor microenvironment scores, stromal scores, and immune scores in most cancer types." (PMID 40356980, 2025). "Our findings indicated a positive association between SF3B6 gene expression and methylation levels at various sites in the DNA promoter region across 11 cancer types, suggesting that increased SF3B6 expression may be regulated by DNA methylation." (PMID 40356980, 2025). "Notably, the methylation levels of cg15544402 and cg01493198 were negatively associated with SF3B6 gene expression in more than half of the cancer types." (PMID 40356980, 2025). "The results suggested a positive association between SF3B6 expression and CNVs in most cancer types, which may partially explain the elevated expression of SF3B6 observed in these cancers." (PMID 40356980, 2025). "In specific cancer types, SF3B6 showed a significant association with MSI and TMB." (PMID 40356980, 2025). "The KEGG analysis demonstrated that the genes interacting with SF3B6 were enriched in pathways related to splicing, mismatch repair, DNA replication, RNA degradation, and several cancer-related pathways." (PMID 40356980, 2025). "Given that amplification and deep deletion represent copy number variations (CNVs), we further explored the correlation between SF3B6 expression and CNVs across different cancer types." (PMID 40356980, 2025). "Results indicate that SF3B6 was highly expressed in various cancers and regulated by copy number variations and DNA methylation." (PMID 40356980, 2025). "This research lays a foundation and provides direction for future studies on the mechanisms and therapeutic implications of SF3B6 in cancer." (PMID 40356980, 2025). "We initially examined the correlation between SF3B6 gene expression and the infiltration of immune and stromal cells across various cancer types utilizing the ESTIMATE algorithm." (PMID 40356980, 2025). "It will evaluate the correlation of SF3B6 with cancer diagnosis, prognosis, immune infiltration, immune therapy response, and signaling pathways." (PMID 40356980, 2025). "Considering the association of SF3B6 with the tumor microenvironment and immune cell infiltration across various cancer types, we executed a further analysis of the predictive value of SF3B6 in immunotherapy." (PMID 40356980, 2025). "To investigate the role of SF3B6 across pan-cancer, we initially retrieved a network interaction diagram of proteins and genes that interact with SF3B6 from the BioGRID database." (PMID 40356980, 2025). "This research is the first to provide a comprehensive analysis of SF3B6 expression levels, clinical relevance, and potential roles across pan-cancer, further exploring its mechanisms in HCC through bioinformatics and in vitro experimental methods." (PMID 40356980, 2025). "The elevated expression of SF3B6 demonstrated predictive value for cancer diagnosis, prognosis, and responses to immunotherapy." (PMID 40356980, 2025). "We emphasize that SF3B6 has the potential to serve as a biomarker for predicting cancer diagnosis, prognosis, and immunotherapy responses, especially in HCC." (PMID 40356980, 2025).
cancer (continued). "To summarize, this study represents the first comprehensive analysis of the correlation between SF3B6 expression and diagnosis, prognosis, immune infiltration, and immunotherapy response at the pan-cancer level." (PMID 40356980, 2025). "This research aims to conduct a thorough analysis of SF3B6 expression and genetic variation across various cancers using multi-omics data." (PMID 40356980, 2025). "We utilized various databases to systematically examine the expression and genetic variation of SF3B6 across multiple cancer types, assessing its relationship with diagnosis, prognosis, immune infiltration, immunotherapy response, and associated signaling pathways." (PMID 40356980, 2025). "Furthermore, little is known about the role of SF3B6 in other cancer types." (PMID 40356980, 2025). "Immune infiltration analyses based on the XCELL and ESTIMATE algorithms suggested that SF3B6 showed a negative relationship with the levels of infiltration by immune and stromal cells across various cancer types." (PMID 40356980, 2025). "The three central genes, CBR3, SF3B6, and RHPN1, might play important roles in malignancy cancer transformation." (PMID 34876005, 2021). "However, comprehensive multi-omics analyses on the role of SF3B6 in diagnosis, prognosis, immune infiltration, and responses to immunotherapy across various cancers are lacking." (PMID 40356980, 2025). "Additionally, SF3B6 was positively related to CD4+ T helper (Th) two cells and common lymphoid progenitors in most cancer types, while it demonstrated a negative association with the infiltration of other immune cell types." (PMID 40356980, 2025). "Our results demonstrated that SF3B6 expression was positively related to many immune checkpoint molecules in six types of cancer, including LIHC, while demonstrating a negative correlation with most immune checkpoint molecules in seven additional cancers, including LUAD and HNSC." (PMID 40356980, 2025). "However, although preclinical studies with currently available SF3b‐targeting compounds have shown that these are more toxic to cancer cells than to healthy cells, we found that silencing the expression of SF3B1 and SF3B6 proteins also caused considerable toxicity in nonmalignant IMR‐90 fibroblasts." (PMID 28296343, 2017).
tumor (2 papers, 2021 to 2025). "SF3B6 gene expression was positively linked to most MMR-related genes across all tumor types, except in DLBC and UCS." (PMID 40356980, 2025). "Functional enrichment analysis suggests that SF3B6 was closely associated with pathways related to tumor immunity, tumor metabolism, and cell cycle." (PMID 40356980, 2025). "Next, we analyzed the association of SF3B6 expression with various cell infiltrations in the tumor microenvironment by applying the XCELL algorithm." (PMID 40356980, 2025). "The analysis demonstrated that SF3B6 exhibited good diagnostic value in 26 tumor types (AUC >0.7)." (PMID 40356980, 2025). "Additionally, SF3B6 demonstrated associations with tumor metabolic pathways, such as the unfolded protein response, reactive oxygen species pathways, oxidative phosphorylation, mTORC1, glycolysis, fatty acid metabolism, and protein secretion." (PMID 40356980, 2025). "We demonstrated that SF3B6 was positively related to the majority of MMR-related genes across all tumor types except for DLBC and UCS." (PMID 40356980, 2025). "Considering the correlation between SF3B6 and the tumor microenvironment along with cell infiltration, we analyzed the predictive significance of SF3B6 for immunotherapy responses." (PMID 40356980, 2025). "We initially obtained gene expression data for SF3B6 from the TCGA database and conducted unpaired differential analysis between tumor tissues and adjacent non-tumor tissues." (PMID 40356980, 2025). "SF3B6 also negatively correlated with tumor metabolism-related pathways, including fatty acid synthesis, xenobiotic metabolism, bile acid metabolism, oxidative phosphorylation, and fatty acid metabolism." (PMID 40356980, 2025). "Due to the unavailability of adjacent samples for certain tumor types, we obtained SF3B6 gene expression data from both the TCGA and GTEx databases to perform unpaired differential analysis between tumor tissues and normal tissues." (PMID 40356980, 2025). "To validate the reliability of these findings, we performed Western blot analysis on six paired samples of HCC and adjacent normal tissues, which further confirmed the upregulation of SF3B6 expression in human HCC tumor tissues." (PMID 40356980, 2025). "Our study indicates that SF3B6 may induce tumor immune suppression by promoting the differentiation of Th2 cells." (PMID 40356980, 2025). "Next, we examined the phosphorylation of SF3B6 in mouse tumor tissues." (PMID 34470609, 2021). "Additionally, correlation analysis of immune phenotype scores indicated that in COAD, KIRC, LIHC, LUAD, STAD, THCA, and UCEC, tumor patients with low SF3B6 expression were anticipated to experience improved immunotherapy responses following treatment with CTLA-4 or PD-1 blockade." (PMID 40356980, 2025). "GSEA results suggested that SF3B6 was enriched in pathways associated with the cell cycle, DNA replication, apoptosis, tumor immunity, and tumor metabolism in HCC, indicating that SF3B6 may contribute to tumor cell proliferation, tumor microenvironment formation, and tumor metabolic reprogramming." (PMID 40356980, 2025).
SF3B6 also shares sentences with these, for which no sentence is quoted: alcoholic liver diseases (1 paper); colon cancer (1); glioblastoma (1); head and neck cancer (1); liver fibrosis (1); lung carcinoma (1); malaria (1); pancreatic cancer (1).